PRL (prolactin)
Diseases named in the same sentence as PRL in open-access papers (continued):
Sharing a sentence is not in itself a finding about the gene and the disease.
prolactinoma (57 papers, 2011 to 2025). "Diagnostic certainty of a prolactinoma is generally considered when the serum prolactin concentration is >200 ng/mL (SI: >8700 mIU/L) —in rare cases, up to 400 ng/mL (SI: ∼17,400 mIU/L)." (PMID 41140514, 2025). "Namely, elevated baseline PRL levels and cavernous sinus invasion are consistent factors associated with prolactinoma diagnosis and treatment outcomes." (PMID 40113928, 2025). "It is postulated that persistent HH in males with PRLomas is mainly an effect of chronic hypothalamus functional modification caused by the inhibitory effect of PRL, and, to a lesser extent, derives from direct structural damage of the pituitary." (PMID 38370355, 2024). "Up to 25% of male PRLomas are represented by giant PRLomas (gPRLomas), defined as PRL-secreting PAs ≥ 4 cm in diameter, often associated with markedly high serum PRL levels and significant extrasellar extension." (PMID 38370355, 2024). "For prolactinomas, a serum prolactin level of 150 ng/mL is generally considered a diagnostic threshold." (PMID 36147567, 2022). "Prolactinoma management seems to require combination treatment based on the assessment of cardiovascular risk factors as well as serum PRL levels." (PMID 36558529, 2022). "Historically, sellar lesions causing serum prolactin levels greater than 200 ng/mL were considered to be prolactinomas." (PMID 36147567, 2022). "Recently, a somatic mutation in the SF3B1 gene has been described in 20% of prolactinoma patients, showing higher prolactin (PRL) levels." (PMID 33543431, 2021). "The overall recurrence rate after CAB treatment for a prolactinoma is ~50%, which is known to be associated with tumor size and PRL level at diagnosis." (PMID 32849307, 2020). "There is a suggestion that sex-related TGFβ1 expression in the pituitary is associated with sex-related differences in PRLomas pathogenesis and could protect males from excessive lactotroph proliferation, PRL secretion and PRLoma development." (PMID 38370355, 2024). "This study aimed to investigate the behavioral and electrophysiological indices of attentional processing and interference control, as well as the association of these indices with the PRL level in patients with prolactinomas, using the EEG-modified Eriksen flanker task." (PMID 36009154, 2022). "In small sellar lesions with minor stalk deviation, precise preoperative diagnosis of the type of pathology may be impeded by the mild prolactin elevation caused either by prolactinoma and/or the stalk effect." (PMID 36147567, 2022). "Additionally, while sporadic macro-PRLomas typically exhibit a lesser response to DA therapy, our analysis did not reveal any significant association between tumor size and the rate of PRL normalization." (PMID 39439563, 2024). "These could target the defective DNA damage repair in the LFS-associated medulloblastoma, the prolactin autocrine loop in the atypical prolactinoma, the EPHA3/7 and ALK overexpression in the FAP-associated medulloblastoma, and the multi-RTK upregulation in the soft tissue neoplasms." (PMID 35978432, 2022). "MRI revealed a 5.7 cm pituitary macroadenoma and the prolactin level was 466 ng/mL (9914.89 mIU/L) consistent with a prolactinoma." (PMID 41013821, 2025). "In vitro effects of cabergoline, octreotide and pasireotide on prolactin production was also examined in cultured prolactinoma cells." (PMID 41184667, 2025). "Differentiating silent lactotroph adenoma from other NFPA often requires specific immunohistochemical techniques to detect prolactin staining within tumor cells." (PMID 41140514, 2025). "Aggressive prolactinomas represent a subset of prolactin-secreting tumors distinguished by their aggressive growth pattern and resistance to conventional therapies." (PMID 41013821, 2025). "In a subgroup of prolactinoma cultures PAS inhibited PRL secretion with comparable potency to cabergoline." (PMID 41184667, 2025).
prolactinoma (continued). "In conclusion, our results demonstrate that the only significant predictor of hormonal response in DA-treated prolactinomas was baseline PRL level." (PMID 40995599, 2025). "Although SST5-selective SRLs can inhibit PRL release in human prolactinomas, the in vitro studies conducted to date show that they have a weaker effect on PRL inhibition than do DAs." (PMID 41184667, 2025). "Thereby, both elevated baseline prolactin (PRL) levels and cavernous sinus invasion are consistent determinants of prolactinoma diagnosis and treatment outcomes." (PMID 40113928, 2025). "Laboratory tests revealed an elevated prolactin level, and imaging demonstrated a sellar mass, suggesting prolactinoma." (PMID 41013821, 2025). "We found that OCT was not effective in suppressing PRL secretion in vitro, whereas PAS potently suppressed PRL secretion in a subset of prolactinoma cultures." (PMID 41184667, 2025). "This case represents an exception to the widely accepted paradigm that in the presence of a macroadenoma and a confirmed normal PRL level (after avoiding the “hook effect”), a prolactinoma can be discarded." (PMID 39051300, 2024). "In the presence of a pituitary macroadenoma, markedly increased PRL makes the diagnosis of prolactinoma." (PMID 39051300, 2024). "The proposed independent predictors of HH persistence in men PRLomas include higher baseline PRL levels, larger tumor size, lower baseline testosterone levels, hypopituitarism, and visual field defect." (PMID 38370355, 2024). "Our research, in line with the proportion of micro-PRLomas in the entire cohort of the Dutch study, revealed a lower PRL normalization rate compared to their findings, standing at 60.9%." (PMID 39439563, 2024). "The PRL levels in the patient were elevated to 92,000 mIU/L (reference range: <500 mIU/L), indicating that the tumor was functioning as a prolactinoma (ADVIA Centaur Prolactin Assay, Siemens Healthcare Laboratory Diagnostics)." (PMID 39553112, 2024). "This case report represents an exception to the paradigm that in the presence of a macroadenoma and normal PRL levels (avoiding the “hook effect”), a prolactinoma can be discarded." (PMID 39051300, 2024). "Most authors agree that in the presence of a macroadenoma and a confirmed normal PRL level (after avoiding the “hook effect”), a prolactinoma can be discarded." (PMID 39051300, 2024). "PRLomas in men, in comparison to women, are usually larger, more invasive and show higher PRL concentration at the time of the diagnosis." (PMID 38370355, 2024). "Our results showed lower rates of normalized PRL, 43.75% for macro-PRLomas and 72% for micro-PRLomas, compared to the response rates reported in sporadic PRLomas." (PMID 39439563, 2024). "Concerning the outcomes of DA therapy as the initial treatment strategy in 41 PRLomas, it was observed that, over an average duration of 10 years, 25 (60.9%) achieved normalized PRL levels, and 17 (41.4%) showed size reduction or became undetectable on MRI." (PMID 39439563, 2024). "In males, PRLomas are notably larger than those in females and, at the time of the diagnosis, are likely to be macroadenomas with high serum PRL concentration." (PMID 38370355, 2024). "The most common type is a somatotroph tumor (50%), either as a pure GH secretor or as PRL-GH co-secretors, followed by lactotroph adenomas and NF-PitNETs, while corticotroph- and TSH-secreting tumors are quite rare." (PMID 37109772, 2023). "Further experiments in various mouse pituitary cell types and rat prolactinoma cells showed that miR-7a2 exerts its effects by inhibiting its target gene Raf1, a known promoter of prolactin production." (PMID 38275385, 2023). "Therapeutic goals for prolactinoma include normalization of prolactin levels, significant tumor reduction, and restoration of function of the anterior and posterior pituitary gland." (PMID 37173679, 2023).
prolactinoma (continued). "It has also been shown that partial resection of a DA resistant prolactinoma can allow prolactin normalization with a lower dose of DA offered post-operatively." (PMID 36928728, 2023). "In lactotroph adenomas, DAs, cabergoline, and bromocriptine are quite effective for PRL normalization (85% of patients) and the reduction in the tumor size (80% of patients) and represent the treatment of choice for most patients." (PMID 37109772, 2023). "The majority of prolactinomas are well controlled by DAs and respond to treatment with serum PRL normalisation, tumour volume reduction, and restoration of gonadal function." (PMID 35683457, 2022). "Prolactinoma is the most common subtype of PAs (accounting for up to 60%), of which the main clinical damages are attributed to tumor local mass effects and prolactin oversecretion." (PMID 36009154, 2022). "In the present study, we showed that the level of overproduction of prolactin in patients with prolactinoma correlated with the level of cognitive functioning, which is in line with the results of other studies." (PMID 36581642, 2022). "The test resulted in a stimulation of baseline PRL of less than 300% in all PRLomas, while it was above this cut-off in all the other etiologies." (PMID 35250884, 2022). "Preoperative knowledge if a small sellar lesion with elevated PRL levels is a prolactin-producing adenoma (prolactinoma) or another sort of sellar lesion is of utmost interest for patient counselling and therapeutic decisions." (PMID 36147567, 2022). "So, this review will summarise the current knowledge about the relationship between PRL and pituitary physiology and aim to identify PRL’s role in the pathophysiology of prolactinomas." (PMID 36714572, 2022). "Nevertheless, these prolactin cutoff values were mainly applied to differentiate prolactinomas from other pathologies in mixed cohorts, irrespectively of their tumor size." (PMID 36147567, 2022). "The metoclopramide test resulted in an increase of basal PRL < 300% in all prolactinomas and ≥ 300% in all the other etiologies." (PMID 35250884, 2022). "The evidence presented here suggests a significant role of PRL in the pathogenesis of prolactinomas." (PMID 36714572, 2022). "Histological analysis revealed a sparsely granulated lactotroph adenoma with positive immunostaining for PRL and Ki-67 index >3%." (PMID 35683457, 2022). "The present study provided behavioral and electrophysiological evidence of impaired attentional processing and interference control in patients with prolactinomas and revealed their correlations to PRL levels." (PMID 36009154, 2022). "It has been shown that radiological assessment of prolactinoma invasiveness (Knosp grades) and early postoperative serum PRL levels are significant prognostic factors of early remission following transsphenoidal prolactinoma resection." (PMID 35683457, 2022). "Our patients with PRLomas had a significantly higher value of PRL and all of them had a PRL value ≥ 60 ng/ml." (PMID 35250884, 2022). "The treatment of PRL-secreting tumors, formerly known as prolactinomas, has relied mainly on this physiological characteristic, making dopamine agonists the first therapeutic alternative." (PMID 36714572, 2022). "This in turn leads to prolactin secretion and abnormal growth, finally leading to the development of prolactinoma." (PMID 34286902, 2021). "In contrast, serum prolactin concentrations measured immediately after prolactinoma removal were important for predicting remission: those in remission had significantly lower prolactin concentrations on the 1st postoperative day." (PMID 32733387, 2020). "We evaluated the invasiveness of prolactinomas on the Knosp grading scale and measured serum prolactin concentrations on the first postoperative day." (PMID 32733387, 2020). "Dopamine-agonists (DA) can normalize prolactin levels and lead to reduction in size of the lactotroph adenoma." (PMID 32556793, 2020).
prolactinoma (continued). "In conclusion, radiological assessment of prolactinoma invasiveness (Knosp grades) and early postoperative serum prolactin concentrations are important for predicting outcomes of transsphenoidal prolactinoma resection." (PMID 32733387, 2020). "HMGA2 has been shown to be rearranged and amplified in lactotroph adenomas, and transgenic mice with Hmga2 overexpression develop PAs with prolactin and GH secretion." (PMID 33574795, 2020). "Although observation and routine follow-up with serial prolactin levels and imaging is acceptable for patients who are asymptomatic and who have a microadenoma, most patients diagnosed with a prolactinoma will require treatment." (PMID 32556793, 2020). "Clinical manifestations of a prolactinoma can result from the overproduction of prolactin and mass effects." (PMID 32849307, 2020). "Similar to other investigators, we showed that preoperative serum prolactin concentrations correlated positively with prolactinoma size, tumor invasiveness, and patient age." (PMID 32733387, 2020). "The diagnosis of a lactotroph adenoma can be inferred in most patients based on the presence of a pituitary adenoma and an elevated prolactin level, which is typically proportionate in magnitude to adenoma size." (PMID 32556793, 2020). "Normalization of PRL and/or tumour shrinkage cannot be achieved with DA treatment in all cases of prolactinomas." (PMID 31847209, 2019). "On the basis of the patient’s serum concentration of prolactin, we diagnosed a prolactinoma and started dopamine agonist therapy with cabergoline." (PMID 30660191, 2019). "In previous reports, DA therapy was the first-line medical treatment even for giant PRLomas, because normalization of PRL and significant tumor shrinkage were achieved in the majority of cases." (PMID 30660191, 2019). "In prolactinomas, the average numbers of cells expressing given markers were: prolactin 45.8±5.6% (from 40% to 55%); ACTH 0.05±0.08% (0-0.2%); GH 0.03±0.04% (0.04-0.1%); and NeuroD1 98.9±0.6% (98.2-99.3%)." (PMID 30719226, 2019). "It is encountered in the presence of excessively high PRL levels (as seen with macro- or giant prolactinomas) which saturate the antibodies used in the two-site immunoradiometric assay leading to artificially low PRL values." (PMID 31847209, 2019). "Dopamine agonists such as bromocriptine and cabergoline are the predominant treatment drugs for prolactinoma by inhibiting prolactin secretion and shrinking tumor size." (PMID 30740089, 2018). "The lactotroph adenoma cells express dopamine receptors, and DAs effectively suppress prolactin secretion and shrink the tumor by binding the cell-surface dopamine receptors in most patients." (PMID 30740089, 2018). "The normalization of serum prolactin (PRL) levels and shrinkage of tumors are among the major goals of treatment in patients with prolactinomas." (PMID 30740089, 2018). "Over-production of PRL was controlled by pharmacological therapy with dopamine agonist (cabergoline) in 30 patients affected by PRLoma (50% of patients affected by PRLomas)." (PMID 30428914, 2018). "In mixed somatotroph/lactotroph adenomas, the degree of hormone expression and distribution of GH and PRL-positive cells vary among cases." (PMID 27245663, 2016). "In order to evaluate if obtained cells maintain hormone-secreting cells, cell cultures from somatotrophic and lactotrophic adenomas were stained for GH or PRL." (PMID 27340409, 2016). "Selective estrogen receptor modulators (SERMs) lower prolactin (PRL) levels by blocking estrogen’s effects on lactotroph cells, which can otherwise raise PRL and promote cell growth; in resistant prolactinomas, SERMs like tamoxifen and raloxifene have been shown to reduce PRL levels by 20%." (PMID 41013821, 2025).
prolactinoma (continued). "In this retrospective cohort study of 149 prolactinoma patients treated with first-line transsphenoidal surgery (TSS) or dopamine agonist (DA) therapy, we evaluated preoperative prolactin (PRL) levels and cavernous sinus invasion as factors associated with long-term remission." (PMID 40113928, 2025). "SST5 specifically regulates PRL secretion from human prolactinoma cells in vitro." (PMID 41184667, 2025). "Moreover, the exceedingly rare prolactin-secreting carcinomas, constituting a mere 0.2% of adenohypophyseal tumors, underscore the rarity and complexity of aggressive transformation in prolactinomas." (PMID 41013821, 2025). "Serum prolactin (PRL) should be measured to evaluate for prolactinoma." (PMID 39051300, 2024). "Prolactin-secreting PA (prolactinomas) account for approximately 53% of PAs and arise from cells of lactotroph lineage Compared with men, women are approximately ten times more likely to develop prolactinomas and are diagnosed at a younger age; however, the tumors tend to be smaller." (PMID 39051300, 2024). "Prolactin-secreting PAs (PRLomas) (53.5%) and microadenomas (65.5%) were most common." (PMID 39439563, 2024). "A PA with a circulating PRL greater than 250 ng/mL is considered a prolactinoma." (PMID 39051300, 2024). "Additionally, the coefficient of variability (CV) was in the range of 3–5%, with assay changes over the many years of data collection of PRL/testosterone/LH/FSH values in patients with lactotroph adenomas, starting from 1996 until December 2015." (PMID 39085672, 2024). "Eighteen (72%) micro-PRLomas achieved normalization of PRL levels." (PMID 39439563, 2024). "All of them are related to paracrine/autocrine PRL effects in the pituitary; for all, there are already described pharmacological modulators and thus are relevant pharmacological targets for potential aggressive prolactinomas." (PMID 36714572, 2022). "Lactotroph tumors (commonly referred to as prolactinomas) are a type of Pit-1-linage PitNET characterized by the presence of PRL, either in paranuclear dot-like expression (“Sparsely granulated lactotroph tumor”) or a diffuse cytoplasmatic manner (“Densely granulated lactotroph tumor”)." (PMID 36714572, 2022). "Similarly, in this study, the authors found that in female prolactinomas hypointensity was related to younger age at diagnosis, higher baseline PRL levels, and DA resistance." (PMID 35683457, 2022). "The approach to the knowledge of how prolactinomas develop from studying physiological factors that control the intracellular signaling pathways that regulate the proliferation and apoptosis of lactotrophs is critical, and PRL is a promising candidate." (PMID 36714572, 2022). "In conclusion, this is an innovative study that reveals the impaired cognition abilities in prolactinomas, and also proposes the possible cognitive toxicity of oversecreted PRL levels, which provides evidence for further research on the cognitive decline in PAs." (PMID 36009154, 2022). "In this study, we analyzed whether early postoperative serum prolactin concentrations and selected tumor characteristics could predict early, hormonal remission after removal of prolactinomas." (PMID 32733387, 2020). "Invasive giant prolactinomas are a rare type of prolactin-secreting tumors." (PMID 32944476, 2020). "Previous studies suggested that men, elderly patients, patients with large, invasive, or highly proliferating tumors, and patients with high post-operative prolactin concentrations or previous incomplete resections are less likely to achieve remission after surgical removal of prolactinomas." (PMID 32733387, 2020). "Nonetheless, there is no PRL cut-off with perfect diagnostic value differentiating prolactinoma from other tumours." (PMID 31847209, 2019).